RN7SL553P (RNA, 7SL, cytoplasmic 553, pseudogene)
Gene: Miscellaneous RNA gene on chromosome 3 (5,252,926 to 5,253,223, reverse strand). Ensembl gene ENSG00000241227.
Homologues: Orthologues: chimpanzee Metazoa_SRP (99% identical), macaque Metazoa_SRP (86% identical). Paralogues in human: RN7SL2 (83% identical), RN7SL1 (83% identical), RN7SL3 (81% identical), RN7SL357P (81% identical), RN7SL336P (81% identical), RN7SL88P (80% identical), RN7SL743P (79% identical), RN7SL126P (79% identical), RN7SL178P (79% identical), RN7SL220P (79% identical), RN7SL444P (79% identical), RN7SL448P (79% identical), and 704 more.